BCL6B (BCL6B transcription repressor)
Description:
Acts as a sequence-specific transcriptional repressor in association with BCL6. May function in a narrow stage or be related to some events in the early B-cell development.
Synonyms: BAZF; ZNF62; ZBTB28
Tractability: Antibody: the Human Protein Atlas places it where antibodies can reach. PROTAC: a small molecule that binds it is known.
Gene: Protein-coding gene on chromosome 17 (7,023,050 to 7,030,290, forward strand). Ensembl gene ENSG00000161940.
Subcellular location: Nucleus
Subcellular location (Human Protein Atlas): Nucleoplasm; Plasma membrane; Vesicles
Gene Ontology:
Molecular function: protein binding; sequence-specific double-stranded DNA binding; DNA-binding transcription repressor activity, RNA polymerase II-specific; RNA polymerase II cis-regulatory region sequence-specific DNA binding
Biological process: negative regulation of transcription by RNA polymerase II; regulation of cell differentiation; regulation of cell population proliferation; regulation of cytokine production; regulation of immune system process; regulation of inflammatory response; type 2 immune response
Cellular component: nucleoplasm; nucleus
Genetic constraint (gnomAD): Loss-of-function variants: 28 observed, 46.67 expected, observed/expected ratio (o/e) 0.6, 90% interval 0.44 to 0.82. The upper end of that interval is the gene's LOEUF score, 0.82, which puts it in group 3 of 6, group 1 being the genes least tolerant of losing a copy. Missense variants: 626 observed, 689.64 expected, observed/expected ratio (o/e) 0.91, 90% interval 0.85 to 0.97. Synonymous variants: 268 observed, 277.88 expected, observed/expected ratio (o/e) 0.96, 90% interval 0.87 to 1.07.
Homologues: Orthologues: chimpanzee BCL6B (99% identical), pig BCL6B (94% identical), dog BCL6B (92% identical), guinea pig BCL6B (91% identical), macaque BCL6B (91% identical), mouse Bcl6b (89% identical), rat Bcl6b (87% identical), zebrafish bcl6b (49% identical). Paralogues in human: BCL6 (54% identical), ZBTB49 (23% identical), ZBTB46 (23% identical), ZBTB21 (22% identical), ZBTB3 (22% identical), ZBTB7B (22% identical), ZBTB12 (20% identical), ZBTB14 (20% identical), GFI1 (17% identical), PRDM13 (17% identical), ZBTB26 (17% identical), ZBTB6 (16% identical), and 16 more.
Diseases named in the same sentence as BCL6B in open-access papers:
BCL6B is named in the same sentence as 40 diseases in open-access papers, as found by Europe PMC text mining. Sharing a sentence is not in itself a finding about the gene and the disease. The quoted sentences say what the papers report.
gastric cancer (7 papers, 2015 to 2025). A primary or metastatic malignant neoplasm involving the stomach. "Moreover, reduced BCL6B levels in cancers like liver and gastric cancer are strongly linked to poor survival outcomes, indicating its potential as a diagnostic and prognostic biomarker." (PMID 41049002, 2025). "BCL6B plays a pivotal role as a potential tumor suppressor in gastric cancer, and promoter hypermethylation, as a plasma DNA biomarker, is associated with poor survival of gastric cancer patients." (PMID 25970780, 2015). "Data from The Cancer Genome Atlas (TCGA) reveal upregulated BCL6B expression in head and neck squamous cell carcinoma, cholangiocarcinoma, clear cell renal carcinoma, hepatocellular carcinoma, gastric cancer, thyroid cancer, and glioblastoma." (PMID 41049002, 2025). "BCL6B has been shown to play a critical role in the initiation and progression of multiple solid tumors, including hepatocellular carcinoma, gastric cancer, colorectal cancer, breast cancer, cervical cancer, and various lymphomas." (PMID 41049002, 2025). "In mice, inactivation of Bcl6b promotes gastric cancer through amplification of the gastric inflammatory response." (PMID 35723340, 2022). "Epigenetic inactivation of Bcl6b promotes gastric cancer through amplification of the gastric inflammatory response in vivo and offers a new approach for GC treatment and regenerative medicine." (PMID 31288844, 2019). "BCL6B is regarded as a potential tumor suppressor, and methylation of BCL6B is a marker of poor prognosis in several human cancers, including gastric cancer, hepatocellular carcinoma, and colorectal cancer." (PMID 30286088, 2018). "Re-expression of BCL6B in gastric cancer, hepatocellular carcinoma, and colorectal cancer cell lines can inhibit colony formation, suppress cell viability, induce apoptosis, and restrain their tumorigenicity in nude mice." (PMID 30286088, 2018). "Moreover, knockout of Bcl6b dramatically worsened the severity of gastric cancer and aggravated the inflammatory response in the BaP-induced mice GC model." (PMID 31288844, 2019). "BCL6B is a potential tumor suppressor in human gastric cancer, but the regulation and mechanism of BCL6B in human hepatocellular carcinogenesis remain unclear." (PMID 25909168, 2015). "BCL6B was regarded as a potential tumor suppressor and methylation of BCL6B may serve as a poor prognosis marker in gastric cancer." (PMID 25909168, 2015). "As Bcl6b was dramatically downregulated by promoter methylation in our BaP-induced mouse gastric cancer model, we therefore hypothesized that the demethylation drug 5-Aza may ameliorate the BaP-induced inflammatory response during gastric carcinogenesis through re-activated Bcl6b." (PMID 31288844, 2019). "Since BCL6B has been reported to be silenced via its promoter hypermethylation in human gastric cancer, bisulphite genomic sequencing (BGS) analysis was performed, which subsequently revealed that the methylation status of the Bcl6b promoter was elevated during BaP-induced gastric carcinogenesis." (PMID 31288844, 2019).
hepatocellular carcinoma (7 papers, 2015 to 2026). A malignant tumor that arises from hepatocytes. "While BCL6 has been most widely studied in hematologic malignancies, some solid tumor data, such as hypermethylation of BCL6B correlating with metastasis in hepatocellular carcinoma, point to its involvement in metastatic behavior." (PMID 41597409, 2026). "BCL6B is frequently methylated in human hepatocellular carcinoma and the expression of BCL6B was regulated by promoter region hypermethylation." (PMID 25909168, 2015). "Human BCL6B is a tumor suppressor that inhibits hepatocellular carcinoma metastasis." (PMID 33273587, 2020). "This study is to explore the epigenetic change and mechanism of BCL6B in human hepatocellular carcinoma (HCC)." (PMID 25909168, 2015). "It was reported that BCL6B inhibits hepatocellular carcinoma (HCC) metastases, but the exact role of BCL6B in HCC remains to be investigated." (PMID 25970780, 2015). "The BCL6B gene, affected by a frameshift deletion exclusively in both metastases of PTID 4, is recently reported a novel tumor suppressor gene in hepatocellular carcinoma." (PMID 29293529, 2018). "Stable expression of BCL6B suppressed migration and invasion of MHCC97L cells and significantly reduced the incidence and severity of lung metastasis in an orthotopic mouse model of hepatocellular carcinoma." (PMID 30286088, 2018).
breast carcinoma (6 papers, 2020 to 2026). "Follow-up studies in 2018 revealed that BCL6B functions as a suppressor of breast cancer metastasis, likely via upregulation of E-cadherin and downregulation of VEGFA." (PMID 41049002, 2025). "Simultaneously, BCL6B has been identified as a potential driver of metastatic progression in breast cancer." (PMID 39126025, 2024). "Mechanistic insights suggest that BCL6B suppresses CD24 and CD47 expression, enhancing macrophage phagocytic activity by increasing antibody binding sensitivity, revealing a novel link between immune checkpoint modulation and BCL6B function in breast cancer." (PMID 41049002, 2025).
lymphoma (3 papers, 2014 to 2025). A malignant (clonal) proliferation of B- lymphocytes or T- lymphocytes which involves the lymph nodes, bone marrow and/or extranodal sites. "Understandably, we also observed the B-cell lymphoma protein (BCL6 and its paralog coding gene BCL6B) and other leukemia-related disease genes involved in lymphoma pathogenes, such as BCL11A." (PMID 25649207, 2014).
cervical cancer (2 papers, 2021 to 2025). A primary or metastatic malignant neoplasm involving the cervix. "Conversely, downregulated BCL6B expression is observed in bladder urothelial carcinoma, invasive breast cancer, chromophobe renal carcinoma, renal papillary cell carcinoma, lung adenocarcinoma, lung squamous cell carcinoma, endometrial cancer, and cervical cancers." (PMID 41049002, 2025).
colorectal cancer (2 papers, 2018 to 2025). A primary or metastatic malignant neoplasm that affects the colon or rectum. "Aberrant expression of BCL6B, frequently caused by promoter hypermethylation, is reported in several solid tumors, such as hepatocellular, gastric, breast, and colorectal cancers, as well as hematological malignancies." (PMID 41049002, 2025). "Early studies on BCL6B in colorectal cancer (CRC) revealed that its promoter methylation leads to transcriptional silencing, thereby promoting CRC progression." (PMID 41049002, 2025).
glioblastoma (2 papers, 2024). The most malignant astrocytic tumor (WHO grade IV). "Among these, BCL6B was highly expressed in the tissues of patients with glioblastoma." (PMID 38784036, 2024).
Hepatitis (2 papers, 2015). Inflammation of the liver. "In this study, it demonstrated that BCL6B may play a pivotal role in the process of hepatitis development through upregulation of HGF, but the exactly mechanism needs further investigation." (PMID 25970780, 2015).
Cirrhosis (1 paper, 2015). A chronic disorder of the liver in which liver tissue becomes scarred and is partially replaced by regenerative nodules and fibrotic tissue resulting in loss of liver function. "The opposing directions of BCL6B expression indicate that BCL6B plays an antifibrogenic role at the cirrhosis stage, but when BCL6B is silenced or loses its normal function, tumorigenesis is induced." (PMID 25970780, 2015). "To investigate the positive correlation between BCL6B expression and hepatic cirrhosis in two cohorts of HCC patients (p = 0.001, p = 0.013), we established rat models of liver injury under pathophysiological conditions." (PMID 25970780, 2015). "Decreased BCL6B expression was associated with HCC, but high expression was significantly associated with cirrhosis, as confirmed in both the quantitative PCR and TMA cohorts." (PMID 25970780, 2015). "Moreover, a positive correlation between BCL6B expression and hepatic cirrhosis was found in an analysis of HCC clinicopathological characteristics." (PMID 25970780, 2015). "To test our hypothesis that BCL6B plays a pivotal role in regulating the progression of cirrhosis to HCC, we performed a series of cell and animal experiments to explore the potential responsible mechanisms." (PMID 25970780, 2015). "In this study, we showed for the first time that BCL6B expression is decreased in HCC tissues compared with non-cancer tissues, and BCL6B expression was correlated with the clinicopathological characteristics of HCC, especially cirrhosis." (PMID 25970780, 2015).
differentiated thyroid carcinoma (1 paper, 2025). Differentiated thyroid carcinoma (DTC), also known as papillary or follicular thyroid carcinoma, is a slow-growing malignancy usually presenting in adults as an asymptomatic thyroid mass. "Interestingly, while BCL6B expression is upregulated in differentiated thyroid carcinoma, it is frequently downregulated in many other solid tumors, primarily due to promoter hypermethylation." (PMID 41049002, 2025). "With the exception of differentiated thyroid carcinoma (DTC), where BCL6B has been reported to be upregulated, studies in other investigated cancer types consistently demonstrate downregulation of BCL6B expression." (PMID 41049002, 2025).
fibrosis (1 paper, 2015). the formation of excess fibrous connective tissue in an organ or tissue in a reparative or reactive process. "The results here suggest that BCL6B may be an ideal candidate for predicting the progression of both HCC and liver fibrosis, since BCL6B expression was reduced in HCC tissues but enhanced in fibrotic tissues." (PMID 25970780, 2015).
gastric tumour (1 paper, 2019). "Based on this established mouse GC model, we induced gastric tumours within wildtype and Bcl6b−/− mice, and then treated with or without the demethylation drug 5-Aza-2′-deoxycytidine (5-Aza) to induce Bcl6b reactivation." (PMID 31288844, 2019). "Taken together, these results demonstrated that 5-Aza effectively prevented BaP-induced gastric tumour development in a Bcl6b-dependent manner." (PMID 31288844, 2019). "To further address whether 5-Aza has any beneficial effects on GC formation, we identified and quantified the gastric tumour load in BaP-treated Bcl6b−/− mice and wildtype controls with or without 5-Aza treatment." (PMID 31288844, 2019).
germ cell tumor (1 paper, 2014). A benign or malignant, gonadal or extragonadal neoplasm that originates from germ cells. "Bcl6b encodes a transcription factor and downstream target of FGF2 capable of promoting germ cell tumors." (PMID 25070369, 2014).
hepatitis B infection (1 paper, 2015). "BCL6B protein expression in cancer tissues from the quantitative PCR cohort was significantly correlated with clinicopathological features such as hepatitis B infection, liver cirrhosis and portal vein tumor thrombus (PVTT) (p < 0.05 for all)." (PMID 25970780, 2015).
infertile (1 paper, 2017). "DMRTB1 was a down-regulated common gene among MArrest, oligospermia and Ikbkap KO, GPR137B was common among teratospermia, Bcl6b and Pou3f1 KD, and LMNB2 was common among Bcl6b, Etv5 and Pou3f1 KD infertile mice." (PMID 29150651, 2017). "Additionally, the Arpc1b gene was up-regulated in Bcl6b, Etv5, Pouf31 and Dazap1 KD, and Alcam was up-regulated in Bcl6b, Etv5, Pouf31 and Ing2 KD infertile mice." (PMID 29150651, 2017).
liver cirrhosis (1 paper, 2015). "Moreover, the correlation between BCL6B expression and liver cirrhosis and PVTT was confirmed in the HCC TMA cohort." (PMID 25970780, 2015).
liver fibrosis (1 paper, 2015). "Overexpression of liver-specific BCL6B by lentiviruses in vivo not only ameliorated hepatocellular damage and inflammation but also attenuated the procession of liver fibrosis in the CLI model." (PMID 25970780, 2015). "The causal relationship and physiological role of BCL6B in the development of liver fibrosis must be elucidated to demonstrate the role played by BCL6B in HCC." (PMID 25970780, 2015). "Significantly higher levels of HA, a marker of liver fibrosis, were found in the serum of sh-BCL6B-transfected rats, compared with control (sh-Ctrl) rats." (PMID 25970780, 2015). "Furthermore, inhibiting BCL6B expression by adenovirus-mediated RNA interference aggravated liver fibrosis in the ALI model, as expected." (PMID 25970780, 2015). "Since BCL6B ameliorated the development of liver fibrosis in CLI rat models, we attempted to promote the progression of liver fibrosis by blocking BCL6B expression in the ALI model." (PMID 25970780, 2015). "In contrast, under the no treatment conditions, neither LV-BCL6B-transfected nor sh-BCL6B-transfected rats showed any significant differences in inflammatory cell infiltration or liver fibrosis, compared with control liver tissues." (PMID 25970780, 2015). "BCL6B inhibited the activation of HSC though upregulation of HGF, a well-known antifibrogenic mediator, leading to amelioration of hepatocellular damage and liver fibrosis." (PMID 25970780, 2015). "In contrast, neither sh-BCL6B-transfected nor control rats showed significant liver fibrosis under the no treatment conditions." (PMID 25970780, 2015). "In contrast, neither BCL6B Tg nor control rats showed significant liver fibrosis under the no-treatment conditions." (PMID 25970780, 2015).
lymph node metastasis (1 paper, 2018). "In our study, methylation of some CpG units in the BCL6B promoter region was associated with clinicopathologic characteristics of tumor patients, including tumor size, lymph node metastasis, and patient sex." (PMID 30286088, 2018).
medulloblastoma (1 paper, 2021). A malignant, invasive embryonal neoplasm arising from the cerebellum. "Incidentally, CAG repeats were recently associated with three genes potentially involved in medulloblastoma: RAI1, BCL6B, and TNS1." (PMID 33765058, 2021).
memory impairment (1 paper, 2022). "As a result, 3 DEmRNAs from CCI with memory impairment model rats (ATF3, C1QC, and CD68) and 13 DEmRNAs from SNI and CCI models (ADAMTS2, BCL6B, CLCF1, RBP1, and TPBG, among others) overlapped with SNI and CCI models, respectively." (PMID 35547819, 2022).
teratospermia (1 paper, 2017). "The higher number of common up-regulated genes was found between Etv5 KD and Pou3f1 KD, with 53 genes, Bcl6b KD and Etv5 KD, with 19 genes, Bcl6b KD and Pou3f1 KD, with 14 genes, MArrest and teratospermia, with 12 genes, and MArrest and Ing2 KO, with nine common genes." (PMID 29150651, 2017).
thyroid cancer (1 paper, 2025). "Notably, BCL6B negatively correlates with CD8+ T cell infiltration, suggesting a unique immune modulation role in DTC, potentially related to the endocrine nature of thyroid cancer." (PMID 41049002, 2025).
Tinnitus (1 paper, 2023). Tinnitus is an auditory perception that can be described as the experience of sound, in the ear or in the head, in the absence of external acoustic stimulation. "Meanwhile, down-regulated genes between the tinnitus and the control group were Car3, Egr2, Bcl6b, C1qtnf12, Cartpt, LOC108348062, Nr4a3, Gprc5a, LOC103690128, and Angptl6." (PMID 37190538, 2023).